HOXA7 (homeobox A7)
Diseases named in the same sentence as HOXA7 in open-access papers (continued):
Sharing a sentence is not in itself a finding about the gene and the disease.
acute myeloid leukemia (3 papers, 2017 to 2025). Acute myeloid leukemia (AML) is a group of neoplasms arising from precursor cells committed to the myeloid cell-line differentiation. "Conversely, AP-2α activated Hoxa7/9 and the Hox cofactor Meis1 to enhance the proliferation and cell survival of acute myeloid leukemia (AML) cells." (PMID 31534499, 2019). "High expressions of HOXA7, HOXA9, and HOXA10 are frequently seen in acute myeloid leukaemia (AML) and the overexpression of HOXA9 is linked to a poor prognosis." (PMID 28515451, 2017). "Additionally, in acute myeloid leukemia (AML), WBP5 overexpression has been associated with poor prognosis, correlating with increased expression of HOX gene cluster (HOXA5, HOXA7, HOXA9, and HOXA10), MEIS1, and FOXC1." (PMID 40002180, 2025).
brain tumor (3 papers, 2017 to 2025). "By a forward stepwise approach with an entry limit of p < 0.05, only CD133 expression (p = 0.021) and HOXA7 expression (p = 0.001) were independent prognostic markers in brain tumor patients." (PMID 28055976, 2017).
glioblastoma (3 papers, 2014 to 2023). The most malignant astrocytic tumor (WHO grade IV). "Above all, some studies have found that down-regulated SNHG16 inhibits HOXA7 by sponging miR-128-3p to prevent the development of glioblastoma." (PMID 34092219, 2021). "Previous research has reported that LINC00511 could regulate trophoblast cell proliferation, apoptosis, invasion, and autophagy through the mir-31-5p/homeobox A7 axis, and promote temozolomide resistance in glioblastoma cells." (PMID 37434634, 2023).
hepatocellular carcinoma (3 papers, 2022 to 2024). A malignant tumor that arises from hepatocytes. "It has been shown that HOXA7 expression is elevated in metastatic hepatocellular carcinoma, enhancing the metastasis of hepatocellular carcinoma, and is associated with a poor prognosis for patients." (PMID 35693013, 2022). "HOXA7 promotes hepatocellular carcinoma through cyclin E1/CDK2, inducing proliferation, migration, colony formation, and tumorigenesis in vivo." (PMID 39596630, 2024).
meningioma (3 papers, 2013 to 2020). A generally slow growing tumor attached to the dura mater. "have shown that HOXA7 is a methylation target associated with aggressive behavior in meningiomas." (PMID 33363022, 2020). "Similar to TIMP3, repression of HOXA7, HOXA9, and HOXA10 in meningioma is also associated with clinically aggressive behaviour." (PMID 26101774, 2015). "DNA methylation levels of HOXA7, HOXA9, and HOXA10 were reported to be significantly higher in atypical and anaplastic meningiomas than in the benign form." (PMID 26101774, 2015). "DNA methylation levels of HOXA7, HOXA9 and HOXA10 were reported significantly higher in WHO grade II and III meningiomas than in grade I (benign) meningiomas." (PMID 23349797, 2013).
myeloid leukemia (3 papers, 2019 to 2025). A clonal proliferation of myeloid cells and their precursors in the bone marrow, peripheral blood, and spleen. "Recent studies have shown the activation of HOXA9 and HOXA7 via proviral integration in a mouse model of myeloid leukemia." (PMID 38944027, 2025).
non-small cell lung carcinoma (3 papers, 2014 to 2023). A group of at least three distinct histological types of lung cancer, including non-small cell squamous cell carcinoma, adenocarcinoma, and large cell carcinoma. "In a methylation study on the early diagnosis of non-small cell lung cancer, it has found that the expression of HOXA7 methylation had high sensitivity and specificity in the diagnosis of non-small cell lung cancer." (PMID 33363022, 2020). "High-frequency methylation profiles have been reported for several cancer-specific genes, including SOX17, TAC1, HOXA7, CDO1, HOXA9, and ZFP42, in both preoperative plasma and sputum samples from lymph node-negative stage I and IIA non-small cell lung cancer (NSCLC) patients." (PMID 37840147, 2023).
ovarian tumors (3 papers, 2010 to 2020). "Additionally, the expression of HOXA7 was detected in ovarian tumors exhibiting mullerian-like features and correlated with the generation of anti-HOXA7 antibodies in patients." (PMID 20540809, 2010).
asthma (2 papers, 2020 to 2023). "Furthermore, DNAm markers in HOXA7 and HOXA4 genes have been associated with lung development and asthma, while DNAm in AURKC has been associated with lung function in Latino children with asthma." (PMID 36979655, 2023). "For the remaining genes (airway fibroblasts: HOOK2 and HOXA7; parenchymal fibroblasts: HOXA5, HOXA6, HOXA-AS3, RB1 and NR2F1-AS1), there was no differential gene expression between donors with and without asthma." (PMID 33008450, 2020).
chordoma (2 papers, 2017 to 2021). Chordomas are rare malignant tumors arising from embryonic remnants of the notochord in axial skeleton. "As expected, overexpression of miR-196a-5p significantly reduced HOXA7 levels to 44.3% Taken together, these results suggest that HOX genes are downstream regulatory targets of the miR-196a-5p in chordoma." (PMID 34330313, 2021).
MRKH syndrome (2 papers, 2006 to 2023). "Several genes have been implicated in MRKH syndrome, such as HOXA7, HOXA9–13, HOXD9–13, and WNT4." (PMID 37240886, 2023).
neuroblastoma (2 papers, 2021 to 2022). Neuroblastoma (NB) is the most common solid, extracranial childhood tumor. "SNHG16 silencing reduced HOXA7 expression in neuroblastoma cells, and downregulation of miR‐128‐3p expression reversed this effect." (PMID 35592755, 2022). "ln contrast, the elevating expression of miR‐128‐3p can be rescued by the impact of HOXA7 overexpression, suggesting that miR‐128‐3p functioned as the ceRNA of HOXA7 and miR‐128‐3p is involved in neuroblastoma progression in vitro." (PMID 35592755, 2022). "For example, small nucleolar RNA host gene 16 (SNHG16) facilitated the development and progression of neuroblastoma by upregulating homeobox A7 (HOXA7) expression via sponging miR-128–3p." (PMID 34421622, 2021).
oral squamous cell carcinoma (2 papers, 2022 to 2024). "In oral squamous cell carcinoma, HOXA7 overexpression is linked to aggressive markers such as tumor size, high-grade tumors, vascular and perineural invasion, and lymph node and distant metastases." (PMID 39596630, 2024). "The authors showed that miR196a was upregulated in oral squamous cell carcinoma samples from patients undergoing surgery and radiotherapy, suggesting its interaction with HOXA7 and a potential tumorigenic role." (PMID 39596630, 2024).
osteoporosis (2 papers, 2020 to 2022). A condition of reduced bone mass, with decreased cortical thickness and a decrease in the number and size of the trabeculae of cancellous bone (but normal chemical composition), resulting in increased fracture incidence. "Osteoporosis (OP) and healthy control bone tissues were collected, and the relative expression of miR-920 and HOXA7 was measured." (PMID 32650806, 2020).
ovarian serous carcinoma (2 papers, 2009 to 2019). "The same group showed similar findings with HOXA7; 16/24 patients with moderately differentiated serous ovarian carcinomas were found to have significantly more anti-HOXA7 antibodies compared to healthy controls." (PMID 31382546, 2019). "The same team found similar results in serous ovarian carcinoma with HOXA7." (PMID 31382546, 2019).
prostate carcinoma (2 papers, 2017 to 2023). A carcinoma that arises from epithelial cells of the prostate gland. "HOXA13, HOXA1, HOXA5, HOXA6, HOXA7, HOXA9, and HOXA10 are involved in prostate cancer, and they form a DNA loop with a locus that induces prostate cancer and regulates gene transcription." (PMID 37590265, 2023).
anemia (1 paper, 2018). A reduction in the number of red blood cells, the amount of hemoglobin, and/or the volume of packed red blood cells. "Hoxa7 knockout mice showed reduced megakaryocytic/erythroid progenitors (MEP) and exhibited reticulocytosis and thrombocytopenia without anemia, suggesting that HOXA7 is required for MEP differentiation." (PMID 30154863, 2018).
anencephaly (1 paper, 2019). A rare neural tube defect during pregnancy, resulting in the absence of a large portion of the brain and skull in the fetus. "To investigate the potential effect of expression levels of the selected HOX genes (HOXA1, HOXA7, HOXA9, HOXA10, HOXB1, and HOXB7) in anencephaly, we evaluated 10 anencephaly cranial tissues and 10 matched normal fetus cranial samples by the NanoString technique." (PMID 30992047, 2019). "Notably, the expression of HOXA7, HOXA10, and HOXB7 genes was negatively correlated with CUL4B levels in human anencephaly NTD cases." (PMID 30992047, 2019).
Bernard-Soulier syndrome (1 paper, 2025). Bernard Soulier syndrome (BSS) is an inherited platelet disorder characterized by mild to severe bleeding tendency, macrothrombocytopenia and absent ristocetin-induced platelet agglutination. "Genetic knock-out studies in Hoxa7-TPO cells recapitulate the key function of Klf1 and Nfe2 in red blood cell and platelet development, respectively, while disruption of the von Willebrand receptor gene Gp1ba recapitulates features of human Bernard-Soulier syndrome." (PMID 40775216, 2025).
brachyolmia (1 paper, 2023). Brachyolmia is a rare, clinically and genetically heterogeneous group of bone disorders characterized by short trunk, mild short stature, scoliosis and generalized platyspondyly without significant abnormalities in the long bones. "Finally, the rib and spine phenotypes associated with brachyolmia and metatropic dysplasia could be contributed to the altered expression of HOXA4 to HOXA7 as it has been shown that these genes are associated with rib and spine patterning, and alterations in expression have led to defects." (PMID 36810131, 2023).
endometrial cancer (1 paper, 2019). Primary or metastatic malignant neoplasm involving the endometrium (mucous membrane that lines the endometrial cavity). "Also, poor prognosis of patients with endometrial cancer is associated with higher levels of HOXA4, HOX5, HOXA6, HOXA7, and HOXB9 expression, whereas favorable prognosis of patients with endometrial cancer is associated with higher levels of HOXB5 and HOXB6 expression." (PMID 30866492, 2019).
epithelial ovarian tumors (1 paper, 2022). "Another study found that expression of the homeobox gene HOXA7 is associated with aberrant Müllerian-like differentiation in epithelial ovarian tumors and correlated with the generation of HOXA7-AAb in patients." (PMID 35740550, 2022).
influenza infections (1 paper, 2016). "The HOXA7 gene was also shown to code an antigen in specific tumor types and could be involved in differentiation programs of immune cell types in response to influenza infections." (PMID 27403523, 2016).
liver fibrosis (1 paper, 2017). "HOXA7, mostly mutated in the high liver fibrosis group, was reported to promote metastasis of HCC with activation of Snail, while decreased expression of GATA2 was correlated with poor prognosis of HCC." (PMID 29212479, 2017).
lymph node metastasis (1 paper, 2022). "Elevated HOXA7 expression was positively correlated with lymph node metastasis, distant metastasis, poor tumor differentiation, high TNM stage, and poor prognosis in CRC patients." (PMID 35183163, 2022).
metastasis (1 paper, 2022). The spread or migration of cancer cells from one part of the body (where they first appeared) to another. "The overexpression of HOXA7 showed a positive correlation with tumor differentiation, lymph node metastasis, distant metastasis, high tumor nodule metastasis (TNM) stage, and KRAS mutation." (PMID 35183163, 2022).
pancreatic ductal adenocarcinoma (1 paper, 2022). An infiltrating adenocarcinoma that arises from the epithelial cells of the pancreas. "Several genes in the 500 kb vicinity of HOXA5 (i.e., HOXA3, HOXA9, HOXA7, HOXA1, EVX1) were also associated with high density lipoprotein (HDL) cholesterol efflux capacity, BMI, and pancreatic ductal adenocarcinoma." (PMID 35836279, 2022).
Pancytopenia (1 paper, 2019). An abnormal reduction in numbers of all blood cell types (red blood cells, white blood cells, and platelets). "HoxA9 is co-expressed with additional HoxA proteins, in particular HoxA5, HoxA7, and HoxA10, in immature hematopoietic populations, which likely accounts for the observation that HoxA9-/- mice manifest only mild pancytopenia." (PMID 31120998, 2019).
papillary thyroid cancer (1 paper, 2018). "Kikuchi et al26 identified multiple genes (HIST1H3J, POU4F2, SHOX2, PHKG2, TLX3 and HOXA7) with frequent epigenetic hypermethylation in papillary thyroid cancer, which might function as potential biomarkers." (PMID 30039914, 2018).
preeclampsia (1 paper, 2024). Preeclampsia is a hypertensive disorder of pregnancy that is characterized by new-onset hypertension with proteinuria presenting after 20 weeks of gestation, and depending on mild or severe forms may initially present with severe headache, visual disturbances, and hyperreflexia. "The involvement of miR-3127-5p in preeclampsia has been documented, attributed to the fact that overexpression of its target gene HOXA7 can reverse the effects of miR-3127-5p in trophoblast cells." (PMID 38814453, 2024).
prostate tumors (1 paper, 2017). "In this study, we demonstrated that 255 DEGs were up/down-regulated in prostate tumors compared with BPH tissues; qRT-PCR also confirmed that the DEGs such as ITGBL1, KRT15, TGM4, and HOXA7 genes were up/down-regulated in PCa tissue and cell lines." (PMID 29285211, 2017).
small cell lung carcinoma (1 paper, 2021). Small cell lung cancer (SCLC) is a highly aggressive malignant neoplasm, accounting for 10-15% of lung cancer cases, characterized byrapid growth, and early metastasis. "HOXA1 and HOXA7 were expressed in small cell lung cancer, while they were not expressed in normal lungs." (PMID 34606634, 2021).
T-cell leukemia (1 paper, 2011). A malignant disease of the T-lymphocytes in the bone marrow, thymus, and/or blood. "In contrast, the expression of Hoxa7, a known PcG target gene during development, which is also involved in T-cell leukemia, was significantly upregulated." (PMID 21624129, 2011).
cancer (24 papers, 2012 to 2023). A tumor composed of atypical neoplastic, often pleomorphic cells that invade other tissues. "As a member of the family of homeobox genes, HOXA7 is associated with cell proliferation, nerve invasion, distant metastasis and degree of tumor differentiation in several cancers." (PMID 32854705, 2020). "As expected, significantly more methylated epialleles of SOX17, CDO1, TAC1, and HOXA7 were detected in cancer patients compared to the benign group." (PMID 37039321, 2023). "Several studies have demonstrated that HOXA7 is involved in tumor metastasis, suggesting that HOXA7 expression is different in different types of cancer." (PMID 35693013, 2022). "Consistent with DNA methylation profiles in plasma, methylation of CDO1, TAC1, SOX17, and HOXA7 were detected more frequently in patients with cancer compared with controls." (PMID 32138766, 2020). "In the present study, higher methylation frequencies of CDO1, TAC1, HOXA7, and SOX17were also observed in the plasma of cancer patients." (PMID 32138766, 2020). "The methylation detection rate of CDO1, TAC1, SOX17, and HOXA7 were significantly higher in cancer group than in the benign group (p < 0.001)." (PMID 32138766, 2020). "As a transcription factor, HOXA7 regulates many critical genes involved in cancer cell proliferation and invasion." (PMID 27677590, 2016). "HOXA7 is a member of the HOX family which was involved in the development of multiple cancer types." (PMID 33363022, 2020). "Among them were five genes with known transcription factor activity (PBX3, HOXB3, LEF1, HOXA7, LBH) and three genes with oncogenic potential (PAPD7, PBX3, LEF1) for which a role in other cancers has been suggested previously." (PMID 32728112, 2020). "The promoter hypermethylation of CDO1, TAC1, HOXA7, and SOX17 were detected more frequently in the plasma of cancer patients compared with controls." (PMID 32138766, 2020). "In urine DNA, some markers like HOXD3, HOXA7, GPR62 and KLK10 were detected with comparable frequency from all cancer patients and are candidates for biomarker panels used for the early detection of PCA." (PMID 31297302, 2019). "A similar fraction of cancer samples showed high methylation in each gene (2/20 for HIST1H3J, 8/20 for POU4F2, 4/20 for SHOX2, 5/20 for PHKG2, 6/20 for TLX3, and 4/20 for HOXA7)." (PMID 24367375, 2013). "Although the potential therapeutic consequences and functions are yet to be determined, multiple genes associated with cancer or implied in non-hematologic malignancies were found as fusion partner genes in our dataset (e.g. CHD4, HOXA7, FOXO3)." (PMID 34340673, 2021).